SNHG3 (small nucleolar RNA host gene 3)
Diseases named in the same sentence as SNHG3 in open-access papers (continued):
Sharing a sentence is not in itself a finding about the gene and the disease.
Obesity (1 paper, 2024). Accumulation of substantial excess body fat. "Given Snhg3 was associated with hepatic nutrition change, the role of Snhg3 was further confirmed by constructing hepatocyte-specific Snhg3 knock-out (Snhg3-HKO) mice that were then induced obesity with a high-fat diet." (PMID 39436790, 2024). "The result showed that Snhg3 was significantly downregulated in the liver of high-fat diet-induced obesity (DIO) mice." (PMID 39436790, 2024). "Here, we found that the expression of hepatic Snhg3 was decreased in high-fat diet (HFD)-induced obesity (DIO) mice." (PMID 39436790, 2024). "Furthermore, the hepatocyte-specific Snhg3 knock-in (Snhg3-HKI) mice were also constructed and subsequently induced obesity with a high-fat diet to detect the function of Snhg3 in the liver." (PMID 39436790, 2024).
prostate tumor (1 paper, 2020). "In conclusion, SNHG3 inhibition could reduce the progression of prostate tumor." (PMID 32248648, 2020). "SNHG3 inhibition could reduce the progression of prostate tumor." (PMID 32248648, 2020).
soft tissue tumors (1 paper, 2022). "Another point we should address is that MYH9::USP6 was first identified in MO, and the novel USP6 fusion partners UBE2G1 and SNHG3 were uncovered in one case with MO and one case with FO, respectively, expanding our knowledge of USP6-associated soft tissue tumors with bone metaplasia." (PMID 36727055, 2022).
tumor (66 papers, 2017 to 2025). "High SNHG3 levels in tumor tissues showed marked associations with clinicopathological characteristics like tumor size, tumor stage, FIGO stage, histological grade, lymph node metastasis, and TNM stage." (PMID 41042421, 2025). "SNHG3, located at 1q35.3, has been implicated in advancing multiple tumor types, including `bladder cancer, hepatocellular carcinoma, and colorectal cancer." (PMID 37348024, 2023). "Next, we analyzed the tumor mutation landscape of RCC1/SNHG3/SNHG12 expression in KICH using the SangerBox tool." (PMID 36148010, 2022). "After observing for 4 weeks, we noticed that, compared with the vector group, the mean tumor volume and weight of the SNHG3-KO group were obviously higher, indicating that loss of SNHG3 facilitated the tumor growth in vivo." (PMID 32284745, 2020). "SNHG3 has been regarded as a prognostic factor in multiple cancer types since its expression level is associated with portal vein tumor thrombus, tumor size, and recurrence." (PMID 33817254, 2020). "In hepatocellular carcinoma, SNHG3 is positively associated with larger tumor size and relapse, in addition to Sorafenib resistance, as a consequence of ceRNA activity on miR-128." (PMID 32318335, 2020). "Overexpression of SNHG3 in these was usually associated with poor prognosis and clinical features, like advanced clinical stage, earlier distant metastasis, and tumor size." (PMID 32802874, 2020). "Transient knockdown of MED18 in SNHG3-deficient cells completely rescued the tumor suppressive phenotypes in GC cells." (PMID 31534128, 2019). "High level of SNHG3 also intimately associated with tumor progression as indicated by the aberrant abundance in the patients with lymph node metastasis compared to the metastasis-negative ones." (PMID 31534128, 2019). "Similarly, SNHG3 has been linked to tumorigenesis and inflammatory processes, with growing evidence pointing to its role in promoting tumor growth and metastasis via interactions with regulatory miRNAs and proteins." (PMID 39969652, 2025). "Furthermore, blockade of mTOR by AZD8055 hampered the tumor-promoting effect from the loss of SNHG3." (PMID 32284745, 2020). "SiRNA-mediated knockdown of SNHG3 has been shown to affect various cellular functions in multiple tumor types." (PMID 41042421, 2025). "So far, several lipid‐associated lncRNAs, including small nucleolar RNA host gene 3 (SNHG3), small nucleolar RNA host gene 6 (SNHG6), and LINK‐A (formerly LINC01139), have been found to be involved in tumor progression." (PMID 40111100, 2025). "Together, these data suggested that SNHG3 can promote the tumor growth and peritoneal dissemination of CRC, and is positively correlated with the expression of β-catenin." (PMID 38725844, 2024). "A. MiRNA Sponging: SNHG3 acts as a ceRNA to sponge various miRNAs, forming intricate networks that influence tumor progression, including effects on cell proliferation, invasion, metastasis, and apoptosis." (PMID 39349640, 2024). "The results demonstrated that SNHG3 expression was significantly correlated with tumor differentiation, TNM stage, and lymph node invasion and metastasis." (PMID 39641310, 2024). "SNHG3, recognized as an oncogenic long non-coding RNA (lncRNA), interacts with miR-3173-5p, a tumor-suppressive microRNA, and ERG, an oncogene." (PMID 39349640, 2024). "Mechanistically, our study found that SNHG3 can play a tumor‐promoting role by interacting with an intracellular target protein." (PMID 36208024, 2023). "In the nude mouse xenograft tumor model; it was observed that the suppression of SNHG3 significantly impeded the enlargement of BC cells." (PMID 37348024, 2023). "Extensive research has revealed that SNHG3 expression is commonly elevated in cancerous tissues, correlating with aggressive tumor characteristics and unfavorable patient prognoses." (PMID 37348024, 2023). "Several previous studies have shown that SNHG3 is widely distributed in the nucleus and cytoplasm of tumor cells." (PMID 36208024, 2023).
tumor (continued). "It was found that, CAFs-EVs and CAFs-EVs-SNHG3 significantly facilitated tumor growth, as evidenced by increased tumor volume and weight, and elevated Ki67-positive rate." (PMID 35922404, 2022). "Among the lncRNAs, eight were overexpressed in tumor tissues (SNHG3, AC099850.4, MIR17HG, AL033527.3, AC091057.1, AC026333.4, AL512506.1, and SCAT2)." (PMID 35778697, 2022). "Among them, the expression levels of C15orf54, AL157935.1, LINC01117 and SNHG3 were different between normal and tumour groups, and all of them were up-regulated in tumours." (PMID 35855425, 2022). "Further, we found significant relation between the aberrant upregulation of SNHG1 and SNHG3 in tumor grade and stage." (PMID 35592519, 2022). "This study contributes to a deeper understanding of the function of SNHG3 in malignant progression of PCa as well as its influence on methionine dependence of tumor cells." (PMID 35123415, 2022). "SNHG3 competitively targets several miRNAs to derepress the degradation of mRNA and binds to proteins to maintain the stability of mRNA, through which SNHG3 enhances tumor development." (PMID 35030969, 2022). "A previous study also demonstrated that SNHG3 overexpression promoted tumor proliferation and migration in ccRCC." (PMID 35558077, 2022). "Aberrant expression of SNHG3 is correlated with worse outcomes of patients through contributing to tumor cell proliferation, migration, and invasion." (PMID 35778697, 2022). "In a subset of tumors, high expression of RCC1/SNHG3/SNHG12 caused enhanced mitotic and DNA damage repair processes in tumor cells, thereby enhancing cell viability and promoting cell proliferation." (PMID 36148010, 2022). "In other studies, SNHG3 was reported to participate in tumor progression in multiple human cancers through other mechanisms." (PMID 35030969, 2022). "The expression levels of C15orf54, LINC01117 and SNHG3 varied between normal and tumour groups, and LINC01117 showed an up-regulated trend in tumours, while C15orf54 and SNHG3 showed a down-regulated trend in tumours." (PMID 35855425, 2022). "For instance, SNHG3 is a novel lncRNA that has been identified to have a tumor-suppressor function during papillary thyroid carcinoma (PTC) development, and its silencing can activate tumor progression by modifying the AKT/mTOR/ERK signaling pathway." (PMID 34885213, 2021). "SNHG3 RNA content is positively correlated with portal vein tumor thrombus tumor size and tumor relapse of HCC patients." (PMID 33859998, 2021). "A growing body of evidence showed that SNHG3 appeared to influence tumor formation and progression by modulating autophagy-related microRNAs, genes, or pathways." (PMID 34970559, 2021). "Consistent with the TCGA data, SNHG3 expression levels were higher in tumor tissues relative to paracancerous samples, and in GC cell lines relative to GES-1 controls." (PMID 34898477, 2021). "We further confirmed these results using a xenograft model system wherein we found that knocking down SNHG3 suppressed tumor growth." (PMID 34898477, 2021). "Among them, SNHG3 has been reported to be related to tumor glycolysis, but the role of most other lncRNAs in glycolysis has not been reported." (PMID 34527595, 2021). "This evidence strongly suggests that SNHG3/miR-214-3p/ASF1B axis promotes HCC recurrence by activating tumor immune tolerance and escape, and PD-1 plays an crucial role in this process." (PMID 34336642, 2021). "Knocking down SNHG3 in GC cells impaired the proliferative, migratory, and invasive activity in vitro and constrained in vivo GC xenograft tumor growth." (PMID 34898477, 2021). "SNHG3 is overexpressed in tumour specimens of ccRCC, which was significantly correlated with unfavourable clinical and pathological features." (PMID 33968736, 2021). "To further verify the in vitro findings, we used a xenograft model to test the tumor-suppressive role of SNHG3 in vivo." (PMID 32284745, 2020).
tumor (continued). "In gastric cancer, lncRNA SNHG3 promotes the tumour progression though regulating MED18 methylation." (PMID 32596993, 2020). "In our study, we first reported that lncRNA SNHG3 was significantly up‐regulated in Bca tissues and positively related to the larger tumour size and postoperative metastasis." (PMID 32596993, 2020). "Upregulation of SNHG3 contributes to biological functions, including tumor cell proliferation, migration, invasion and EMT." (PMID 33292213, 2020). "Studies have demonstrated that SNHG3 is overexpressed in various cancers and considered to function as a novel oncogene in tumor development." (PMID 32802874, 2020). "To illuminate the specific mechanism by which SNHG3 exhibit oncogenic function in tumor cells, we analyzed the potential targets of SNHG3 using bioinformatics databases (miRBase and starBase)." (PMID 31956955, 2020). "SNHG3 primarily competes as a competitive endogenous RNA (ceRNA) that targets tumor suppressor microRNAs (miRNAs) and ceRNA mechanisms that regulate biological processes of tumors." (PMID 33292213, 2020). "Small nucleolar RNA host gene 3 (SNHG3), which is located on 1q35.3, is a novel lncRNA and closely related to tumor development." (PMID 33817254, 2020). "We found that not only the tumor volume but also the tumor weight was decreased with inhibited SNHG3 (*P < .05, **P < .01)." (PMID 32248648, 2020). "Noticeably, our study for the first time uncovered the anti-tumor properties of SNHG3 in cancer and provided novel insights into the mechanisms by which SNHG3 exerts its tumor suppressor function in PTC." (PMID 32284745, 2020). "In univariate analysis, advanced tumor stage/pathological stage/histological grade, metastasis, increased SNHG3/SNHG4 expression and decreased SNHG5/SNHG8 expression were potential risk factors of shorter OS." (PMID 32126023, 2020). "The function of SNHG3 on the growth and metabolism of tumor cells was used by CCK8 and mitochondrial oxygen consumption assays." (PMID 31956955, 2020). "In line with our observations in vitro, overexpression of SNHG3 markedly accelerated xenograft tumor progression in comparison with vector control." (PMID 31534128, 2019). "Consistent with the finding from cell culture, we noticed remarkable increase of SNHG3 in tumor in comparison with normal control in vivo as well." (PMID 31534128, 2019). "Potential contribution to the tumor biology of SNHG3 in this disease was also systematically interrogated." (PMID 31534128, 2019). "The predominance of MED18 in exerting oncogenic activity of SNHG3 was validated by the rescue assay as well, wherein co-knockdown of MED18 significantly reversed the tumor suppressing function elicited by SNHG3-silencing." (PMID 31534128, 2019). "CAF-derived EVs deliver SNHG3 into CRC cells, where SNHG3 sponges miR-34b-5p to upregulate HuR and thereby enhance HuR’s association with HOXC6, increasing HOXC6 expression and driving tumor cell proliferation." (PMID 41200195, 2025). "Some researchers verified the role of CAFs-EVs containing SNHG3 in vivo by establishing a xenograft tumor model and found that SNHG3 promotes CRC cell proliferation by increasing HuR expression through the sponge miR-34b-5p and ultimately enhancing HOXC6 transcription." (PMID 39830506, 2024). "SNHG3 belongs to a lncRNA family known as the small nucleolar RNA host genes (SNHGs) family, of which most members have been reported to participate in the process of tumor progression 19-21." (PMID 38725844, 2024). "Their analyses highlight SNHG3's role in influencing immune infiltration patterns and conferring resistance to various therapeutic inhibitors, alongside its correlation with advanced tumor grades and stages." (PMID 39349640, 2024). "Moreover, it was observed that the expression levels of SNHG3 in serum-derived exosomes were also positively correlated with those in tumor tissues." (PMID 38725844, 2024). "We further analyzed the effect of SNHG3 on tumor growth and metastasis of CRC cells in vivo." (PMID 38725844, 2024).
tumor (continued). "Most of the studies revealed that SNHG3 could work as a miRNA sponge to facilitate tumor progression." (PMID 38725844, 2024). "SNHG3/c‐MYC/BMI1 axis may be a novel target for regulating tumor growth and metastasis in BLCa patients." (PMID 36208024, 2023). "Further, in vitro assays demonstrated that BMI1 knockdown could suppress the SNHG3 activation‐induced tumor promoting effect in BLCa cells." (PMID 36208024, 2023). "However, no significant variation was detected in the expression level of SNHG3 among BC tissues with distinct tumor stages and lymph node metastasis status." (PMID 37348024, 2023). "The sEV-derived lncRNA small nucleolar RNA host gene 3 (SNHG3) could participate in metabolic changes within tumor cells after absorbing sEVs." (PMID 37208722, 2023). "However, for C5orf38 and SNHG3, differences in tumor purity between patients with low and high levels of these two lncRNAs were indicated (p = 0.0005 and p = 0.0013, respectively)." (PMID 36294833, 2022). "Taken together, SNHG3 enhanced tumor progression by targeting miR-214-3p in PC." (PMID 35030969, 2022). "The tumor weight ratio of nude mice in vivo in the sh-SNHG3 group was remarkably lower than that in the sh-NC group, indicating that SNHG3 silence could enhance methionine dependence of PCa cells in nude mice." (PMID 35123415, 2022). "At the same time, RCC1/SNHG3/SNHG12 may in turn influence the regulation of immune cell infiltration in this tumor by directly or indirectly regulating the proliferation and differentiation of some immune cells." (PMID 36148010, 2022). "Our study demonstrated the novel role of the SNHG3/miR-214-3p/TGF-β axis in tumor growth and bone metastasis in PC, indicating that SNHG3 may act as a biomarker and promising therapeutic target against PC." (PMID 35030969, 2022). "In this study, we found that SNHG3 expression was gradually increased from normal prostate tissues, PC/nBM to PC/BM, which implied that SNHG3 might be involved in tumor initiation and bone metastasis in PC." (PMID 35030969, 2022). "The expression of SNHG3 was closely related to tumor clinical stage." (PMID 34898477, 2021). "To identify lncRNAs that may be involved in the progression of GC, we assessed available TCGA data and identified SNHG3 as being significantly upregulated in GC tumor tissues relative to normal control tissue samples." (PMID 34898477, 2021). "Our study, for the first time, demonstrated the anti-tumor effects of SNHG3 in PTC." (PMID 32284745, 2020). "Therefore, through continuous progress of antisense RNA or siRNA and ncRNA vectors, direct silencing of SNHG3 has become an important and powerful new target for tumor treatment." (PMID 33292213, 2020). "Furthermore, SNHG3 involved in the pathologic process of tumor, including cell proliferation, migration, EMT, and apoptosis." (PMID 32802874, 2020). "Taken together, SNHG3 involved in many aspects of tumor development and it may serve as a promising therapy target." (PMID 32802874, 2020). "The strong association of SHNG3 expression with the advanced tumor stage and poor prognosis of PTC patients prompted us to investigate whether SNHG3 was required for PTC cell growth and metastasis." (PMID 32284745, 2020). "Taken together, our results indicated that the decreased expression of SNHG3 might act as a tumor suppressor role and predict poor prognosis in PTC patients." (PMID 32284745, 2020). "Besides, the tumor growth was significantly inhibited by knockdown of SNHG3 in CAFs compared with that in the CAFs/sh-control group." (PMID 31956955, 2020). "Moreover, SNHG3 silencing significantly suppressed the enhanced tumor growth mediated by the inhibition of miR-330 targeting." (PMID 31956955, 2020). "Many studies have shown that compared to normal tissues, tumor tissues have increased abnormally expressed SNHG3, which may be used as potential biomarkers for tumor diagnosis." (PMID 33292213, 2020).